DEFB105A (defensin beta 105A)
Description:
Has antibacterial activity.
Synonyms: BD-5; DEFB-5; DEFB105
Tractability: Antibody: UniProt places it where antibodies can reach, with medium confidence; UniProt predicts a signal peptide or a membrane-spanning region; its Gene Ontology location is reachable by antibodies, with medium confidence.
Gene: Protein-coding gene on chromosome 8 (7,821,004 to 7,823,880, reverse strand). Ensembl gene ENSG00000186562.
Subcellular location: Secreted
Pathways (Reactome):
Immune System: Beta defensins; Defensins
Gene Ontology:
Biological process: innate immune response
Cellular component: extracellular region
Genetic constraint (gnomAD): Loss-of-function variants: 0 observed, 1.47 expected, observed/expected ratio (o/e) 0, 90% interval 0 to 1.57. That is too few expected variants to judge how well the gene tolerates losing a copy. Missense variants: 0 observed, 7.71 expected, observed/expected ratio (o/e) 0, 90% interval 0 to 0.39. Synonymous variants: 0 observed, 1.7 expected, observed/expected ratio (o/e) 0, 90% interval 0 to 1.47.
Homologues: Orthologues: chimpanzee DEFB105A (96% identical), dog DEFB105A (68% identical), rat Defb105a (68% identical), rat Defb105b (68% identical), mouse Defb12 (67% identical), dog DEFB105A (60% identical), mouse Defb35 (46% identical). Paralogues in human: DEFB105B (100% identical).